PAFAH1B3 (platelet activating factor acetylhydrolase 1b catalytic subunit 3)
Description:
Alpha1 catalytic subunit of the cytosolic type I platelet-activating factor (PAF) acetylhydrolase (PAF-AH (I)) heterotetrameric enzyme that catalyzes the hydrolyze of the acetyl group at the sn-2 position of PAF and its analogs and modulates the action of PAF. The activity and substrate specificity of PAF-AH (I) are affected by its subunit composition. Both alpha1/alpha1 homodimer (PAFAH1B3/PAFAH1B3 homodimer) and alpha1/alpha2 heterodimer(PAFAH1B3/PAFAH1B2 heterodimer) hydrolyze 1-O-alkyl-2-acetyl-sn-glycero-3-phosphoric acid (AAGPA) more efficiently than PAF, but they have little hydrolytic activity towards 1-O-alkyl-2-acetyl-sn-glycero-3-phosphorylethanolamine (AAGPE). Plays an important role during the development of brain.
Synonyms: PAFAHG
Tractability: PROTAC: ubiquitination databases record sites on it; its protein half-life has been measured.
Target class: Enzyme; Hydrolase
Gene: Protein-coding gene on chromosome 19 (42,297,023 to 42,303,546, reverse strand). Ensembl gene ENSG00000079462.
Subcellular location: Cytoplasm
Subcellular location (Human Protein Atlas): Intermediate filaments
Pathways (Reactome):
Vesicle-mediated transport: COPI-independent Golgi-to-ER retrograde traffic
Gene Ontology:
Molecular function: identical protein binding; protein binding; protein heterodimerization activity; protein homodimerization activity; 1-alkyl-2-acetylglycerophosphocholine esterase activity; platelet-activating factor acetyltransferase activity; protein-containing complex binding
Biological process: lipid metabolic process; nervous system development; platelet activating factor catabolic process; spermatogenesis
Cellular component: membrane; 1-alkyl-2-acetylglycerophosphocholine esterase complex; cytoplasm; cytosol
Genetic constraint (gnomAD): Loss-of-function variants: 16 observed, 24.01 expected, observed/expected ratio (o/e) 0.67, 90% interval 0.45 to 1.01. The upper end of that interval is the gene's LOEUF score, 1.01, which puts it in group 4 of 6, group 1 being the genes least tolerant of losing a copy. Missense variants: 266 observed, 301.22 expected, observed/expected ratio (o/e) 0.88, 90% interval 0.8 to 0.98. Synonymous variants: 144 observed, 124.01 expected, observed/expected ratio (o/e) 1.16, 90% interval 1.01 to 1.33.
Homologues: Orthologues: chimpanzee PAFAH1B3 (100% identical), macaque PAFAH1B3 (99% identical), rabbit PAFAH1B3 (97% identical), dog PAFAH1B3 (97% identical), pig PAFAH1B3 (97% identical), rat Pafah1b3 (97% identical), mouse Pafah1b3 (96% identical), guinea pig PAFAH1B3 (94% identical), tropical clawed frog pafah1b3 (66% identical), Drosophila melanogaster Paf-AHalpha (42% identical). Paralogues in human: PAFAH1B2 (61% identical), ICE1 (26% identical).
Diseases named in the same sentence as PAFAH1B3 in open-access papers:
PAFAH1B3 is named in the same sentence as 56 diseases in open-access papers, as found by Europe PMC text mining. Sharing a sentence is not in itself a finding about the gene and the disease. The quoted sentences say what the papers report.
breast carcinoma (13 papers, 2014 to 2026). "Blockade of PAFAH1B2 and PAFAH1B3 causes a heightened level of tumor-suppressing lipids and damages cancer pathogenicity in breast cancer and several other types of cancer." (PMID 33494814, 2021). "In the ieu-a-1126 cohort, genes with causal relationships to breast cancer included GNB2, HADH, OAS2, OCIAD2, P4HA2, and PAFAH1B3." (PMID 41424847, 2026). "The expression of growth-inhibitory lipids is increased in breast cancer cells when PAFAH1B3 is blocked." (PMID 37957420, 2023). "A previous study demonstrated that knockdown of PAFAH1B3 impaired the proliferation, migration, and invasiveness of breast carcinoma cells by elevating tumor-suppressing signaling lipids." (PMID 35534807, 2022). "PAFAH1B3 is considered an oncogene and is upregulated in several cancers, including prostate cancer, melanoma, breast cancer and ovarian cancer." (PMID 35534807, 2022). "In line with our findings, it has been reported that PAFAH1B3 knockdown suppressed cells proliferation and impaired cells metastasis in breast cancer and gastric cancer." (PMID 34490100, 2021). "PAFAH1B3 was significantly elevated in breast cancer, colon cancer, ovarian cancer, clear cell renal cell carcinoma (RCC), and UCEC." (PMID 35187070, 2021). "PAFAH1B3, known as one of the most common upregulated metabolic enzymes in cancers, is important for maintaining cancer pathogenicity in breast cancer and head and neck squamous cell carcinoma." (PMID 34136395, 2021). "In accordance with recent studies, PAFAH1B3 was overexpressed in breast cancers and HSCC tumor tissues, making it a promising target for cancer therapeutic intervention." (PMID 34136395, 2021). "In line with our findings, it has been reported that depletion of PAFAH1B3 inhibited cell growth and survival in breast cancer and HSCC cell lines." (PMID 34136395, 2021). "A study identified PAFAH1B3 as a key metabolic driver of breast cancer pathogenicity that is upregulated in primary human breast tumors and correlated with poor prognosis." (PMID 32525929, 2020). "PAFAH1B3 is a critical driver of the pathogenicity of breast cancer by inhibiting tumor-suppressing signaling lipids." (PMID 32489334, 2020). "In addition, through metabolic profiling, PAFAH1B3 expression has been found to be upregulated in breast carcinoma cells, and downregulation of PAFAH1B3 remarkably inhibits breast carcinoma cell proliferation, migration and invasion." (PMID 35534807, 2022). "Metabolomic study indicated that inhibition of PAFAH1B3 suppressed the growth of breast cancer by upregulating the levels of anti-tumor lipids, such as ceramides and several PPARα ligands, indicating that PAFAH1B3 serves as a metabolic oncogene in breast cancer." (PMID 33732641, 2021). "Similarly, PAFAH1B3 was highly expressed in different cancer cell lines including melanoma, ovarian, and breast cancer and was broadly dysregulated in a wide spectrum of cancer types." (PMID 34136395, 2021). "In addition, the reduction of PAFAH1B3 expression substantially impaired cellular survival, motility, aggressiveness and in vivo tumor xenograft growth of triple-negative breast cancer cells, which implied PAFAH1b3 is a critical metabolic driver of breast cancer." (PMID 34136395, 2021). "Blocking PAFAH1B3 and PAFAH1B2 have been shown to extensively affect lipid metabolism and upregulate the expression of lipids that inhibit breast cancer growth." (PMID 34490100, 2021). "Up-regulated genes, such as COL10A1, MMP11, NEK2, PAFAH1B3, KIF4A are highly related to breast cancer." (PMID 28245581, 2017).
gastric cancer (6 papers, 2021 to 2024). A primary or metastatic malignant neoplasm involving the stomach. "For example, LAMA4, SFRP family members, ZHX2, and PAFAH1B3 were found to be associated with immune infiltration of gastric cancer." (PMID 35252219, 2021). "We further examined the association of PAFAH1B3 expression with molecular pathways in gastric cancer." (PMID 33732641, 2021). "In summary, PAFAH1B3 may play a pathogenic role in gastric cancer progression, both acting on tumor cells or on tumor-infiltrating immune cells." (PMID 33732641, 2021). "The proliferation, migration, and immunological infiltration of gastric cancer cells are all facilitated by PAFAH1B3." (PMID 37957420, 2023). "Selective inhibition of PAFAH1B3 has been reported remarkably increased in gastric cancer cells, and high PAFAH1B3 expression was significantly correlated with proliferation, migration and immune infiltration." (PMID 34490100, 2021). "Here, we found that PAFAH1B3 knockdown in gastric cancer cells downregulated the levels of IRS1, Myc, HMGB1, and PTGS2, which were reported to serve as oncogenes in many types of cancers." (PMID 33732641, 2021). "In the present study, infiltration levels of CD8-positive T cells and M1 macrophages were significantly higher in the gastric cancer group with high PAFAH1B3 expression." (PMID 33732641, 2021). "PAFAH1B3 is overexpressed in gastric cancer and knockdown of PAFAH1B3 inhibits proliferation, migration, and activation of oncogenic signaling in gastric cancer cells." (PMID 35187070, 2021). "Since immune cell infiltration is important for the prognosis of gastric cancer patients, we also examined the correlation between PAFAH1B3 expression and the immune cell infiltration scores." (PMID 33732641, 2021). "Taken together, PAFAH1B3 facilitates the proliferation, migration, and the activation of oncogenic signaling in gastric cancer cells." (PMID 33732641, 2021). "Next, we evaluated PAFAH1B3 expression in multiple gastric cancer cell lines, and found relatively higher expression of PAFAH1B3 in BGS-823 and SGC-7901 cells compared with that in AGS and MGS-803 cells." (PMID 33732641, 2021). "Western blot was performed to evaluate the role of PAFAH1B3 on signaling pathways in gastric cancer cells." (PMID 33732641, 2021). "To further explore the functions and pathways affected by PAFAH1B3, we performed correlation analyses between PAFAH1B3 and all other mRNAs in gastric cancer using TCGA data." (PMID 33732641, 2021). "PAFAH1B3 knockdown inhibited the proliferation, migration, and the activation of oncogenic signaling in gastric cancer cells." (PMID 33732641, 2021). "PAFAH1B3 was particularly highly expressed in gastric cancer tissues compared with adjacent normal tissues according to TCGA data." (PMID 33732641, 2021). "Besides, PAFAH1B3 silencing also significantly impaired the migratory ability of gastric cancer cells as evidenced by Transwell assay." (PMID 33732641, 2021). "Our results offer novel insights into the functional role of PAFAH1B3 in gastric cancer." (PMID 33732641, 2021). "Similarly, PAFAH1b3 was also highly expressed in gastric cancer cells and osteosarcoma cells, and PAFAH1B3 knockdown was impaired cancer cell proliferation." (PMID 34490100, 2021). "Finally, we examined the effect of PAFAH1B3 knockdown on the apoptosis and proliferation of gastric cancer cells." (PMID 33732641, 2021). "PAFAH1B3 was highly expressed in many types of tumors including gastric cancer." (PMID 33732641, 2021). "Transwell assay was used to evaluate the impact of PAFAH1B3 on gastric cancer cell migration." (PMID 33732641, 2021). "Our findings suggest that PAFAH1B3 may be an oncogene in gastric cancer." (PMID 33732641, 2021). "Further analyses demonstrated that PAFAH1B3 knockdown inhibited the proliferation of the AGS and MGC-803 gastric cancer cell lines." (PMID 33732641, 2021).
gastric cancer (continued). "To explore the biological effects of PAFAH1B3 on gastric cancer cell proliferation, we knocked down PAFAH1B3 expression in BGS-823 and SGC-7901 cells via two PAFAH1B3 shRNA, and validated the successful silence of PAFAH1B3 expression in these two cell lines." (PMID 33732641, 2021). "However, the role of PAFAH1B3 in gastric cancer remains unknown." (PMID 33732641, 2021). "The negative effect of PAFAH1B3 on gastric cancer cell proliferation was further confirmed by colony-formation assay." (PMID 33732641, 2021). "Particularly, high PAFAH1B3 expression was observed in STAD gastric cancer in the TCGA cohort compared with the adjacent tissues, suggesting that PAFAH1B3 may play a role in the pathogenesis of gastric cancer." (PMID 33732641, 2021).
lung adenocarcinoma (5 papers, 2021 to 2025). A carcinoma that arises from the lung and is characterized by the presence of malignant glandular epithelial cells. "Besides, high expression of PAFAH1B3 was also associated with overall survival in adrenocortical carcinoma (P=0.00035), acute myeloid leukemia (P=0.032), lung adenocarcinoma (P=0.008), mesothelioma (P=0.0022), sarcoma and skin cutaneous Melanoma (P=0.0038)." (PMID 34490100, 2021). "Analysis of public databases validated the elevated PAFAH1B3 expression in lung adenocarcinoma and positioned PAFAH1B3 as a promising candidate for prognostic marker and potential therapeutic target in lung cancer treatment." (PMID 41009369, 2025). "Reportedly, elevated expression of PAFAH1B3 affects EMT, thereby promoting papillary thyroid carcinoma and lung adenocarcinoma cell proliferation and metastasis." (PMID 41009369, 2025).
liver cancer (3 papers, 2021 to 2025). An epithelial or non-epithelial malignant neoplasm that arises from the liver. "Transfection of artificially synthesized eccDNA PAFAH1B3 into the liver cancer-associated cell line Sk-Hep1 and liver cancer cell line Huh7 showed a dose-dependent effect on eccDNA PAFAH1B3 expression." (PMID 41009369, 2025). "The results showed that eccDNA PAFAH1B3 was enriched in liver cancer tissues, which is consistent with the sequencing results of this study." (PMID 41009369, 2025). "More importantly, results demonstrated that PAFAH1B3 was upregulated in liver cancer cells lines and that knockdown of this gene significantly inhibited cell proliferation, migration, and invasion in liver hepatocellular carcinoma (LIHC)." (PMID 35187070, 2021). "In addition, we investigated the effects of eccDNA PAFAH1B3 on liver cancer cell proliferation, migration, invasion, and apoptosis using EdU, Transwell, and flow cytometry assays." (PMID 41009369, 2025). "Furthermore, Transwell experiments revealed that the overexpression of eccDNA PAFAH1B3 significantly enhanced the migration and invasion abilities of liver cancer cells (p < 0.001)." (PMID 41009369, 2025). "EccDNA PAFAH1B3 may enhance the proliferation, migration, and invasion of liver cancer cells while inhibiting apoptosis by promoting the expression of PAFAH1B3." (PMID 41009369, 2025). "Moreover, evidence suggests that PAFAH1B3 is upregulated in liver cancer cell lines, and knockdown of this gene significantly inhibits cell proliferation, migration, and invasion in HCC." (PMID 41009369, 2025). "Besides previously reported dysregulated genes, the current study identified new candidate genes with a putative role in liver cancer, e.g. C1orf35, PAFAH1B3, ZNF219 and others." (PMID 33541355, 2021).
lung carcinoma (3 papers, 2023 to 2025). "Significantly, publicly accessible dataset revealed that PAFAH1B3 is not only aberrantly expressed but also harbors potential as a robust prognostic biomarker for lung cancer prognosis and therapeutics." (PMID 39553628, 2024). "Overall, our research positioned PAFAH1B3 as a promising candidate for prognostic marker and potential therapeutic target in lung cancer treatment." (PMID 39553628, 2024). "Through comprehensive subsequent proteomic analysis and in vitro experiments, we have delineated the role of the exosomal protein PAFAH1B3 in augmenting the metastatic propensity of lung cancer cells." (PMID 39553628, 2024). "Mechanistically, the binding of HOMER3 and PAFAH1B3 activates the transcriptional regulation of mitochondrial genes by GABPB1 in lung cancer cells." (PMID 38081871, 2023). "Most notably, with corroborating data analysis and in vitro validation, PAFAH1B3 is identified as not merely overexpressed but also stands as a promising candidate for a potent prognostic biomarker and therapeutic target in lung cancer." (PMID 39553628, 2024).
osteosarcoma (3 papers, 2021). A usually aggressive malignant bone-forming mesenchymal neoplasm, predominantly affecting adolescents and young adults. "In consistence with the literature, we found EIF4EBP1, MYC, PTGS2 were down-regulated in PAFAH1B3 knockdown osteosarcoma cells, resulting the deficiency in tumor growth and proliferation." (PMID 34136395, 2021). "In vitro, loss-of-function assay was performed to explore the role of PAFAH1B3 in osteosarcoma cells." (PMID 34136395, 2021). "However, the association between PAFAH1B3 expression and clinical characteristics of osteosarcoma patients requires further investigation." (PMID 34136395, 2021). "Thus, it would be our future interest to investigate the underlying mechanisms and direct substrates of PAFAH1B3 in osteosarcoma." (PMID 34136395, 2021). "Overall, this study has paved a foundation for elucidating PAFAH1B3 affects proliferation and apoptosis in osteosarcoma." (PMID 34136395, 2021). "Tumor xenograft growth assay was used to verify the effect of PAFAH1B3 knockdown on osteosarcoma growth in vivo." (PMID 34136395, 2021). "In this study, we identified that PAFAH1B3 was highly expressed in human osteosarcoma tumor tissues compared to normal bone tissues." (PMID 34136395, 2021). "Chip assay was carried out to investigate the mechanism in osteosarcoma proliferation regulated by PAFAH1B3." (PMID 34136395, 2021). "Secondly, in the current study, we mainly focused on the proliferative function of PAFAH1B3 in osteosarcoma, the prometastatic role of PAFAH1B3 requires further investigation." (PMID 34136395, 2021). "PAFAH1B3 expression was detected by immunohistochemistry in 83 osteosarcoma tissues and 44 paired adjacent normal bone tissues." (PMID 34136395, 2021). "PAFAH1B3 was significantly overexpressed in osteosarcoma tumor samples (62.7%, 52/83), but was hardly measured in the matching non-tumor tissues (22.7%, 10/44) (P < 0.01)." (PMID 34136395, 2021). "Aberrant higher expression of PAFAH1B3 promotes the cell proliferation and inhibits cell apoptosis of osteosarcoma." (PMID 35187070, 2021). "Here, we detected the expression patterns of PAFAH1B3 in osteosarcoma tissues and the adjacent normal bone samples." (PMID 34136395, 2021). "Taken together, these data suggest that the proliferative effect of PAFAH1B3 in osteosarcoma is related to the regulation of the expression of EIF4EBP1, MYC, PTGS2 and RPS6KB1." (PMID 34136395, 2021). "MTT assay, Celigo image cytometry and clone formation assay were performed to investigate the effects of PAFAH1B3 knockdown on proliferation of osteosarcoma cells." (PMID 34136395, 2021). "The expression level of PAFAH1B3 in osteosarcoma tumor tissues (n=83) and corresponding normal bone specimens (n=44) was detected by IHC." (PMID 34136395, 2021). "Accordingly, lentiviral-mediated siRNA infection was an effective way to knockdown PAFAH1B3 in osteosarcoma cells." (PMID 34136395, 2021). "Moreover, depletion of PAFAH1B3 inhibits the osteosarcoma cell proliferation and induced cell apoptosis in vitro, and also reduced osteosarcoma growth in vivo." (PMID 35187070, 2021). "Moreover, PAFAH1B3 knockdown inhibited osteosarcoma cell proliferation and promoted apoptosis in vitro, and also suppressed osteosarcoma growth in vivo." (PMID 34136395, 2021). "Moreover, loss-of-function assay was conducted in vitro to explore the biological function of PAFAH1B3 in tumorigenesis of human osteosarcoma cell lines." (PMID 34136395, 2021). "Although, PAFAH1B3 plays pivotal roles in proliferation, migration and invasion of multiple cancer types, the precise biochemical functions of PAFAH1b3 and the subsequent regulating mechanisms in osteosarcoma remain poorly understood." (PMID 34136395, 2021). "Loss-of-function assay was carried out to explore the role of PAFAH1B3 in osteosarcoma cells." (PMID 34136395, 2021). "This research confirmed that PAFAH1B3 could be a novel therapeutic target for osteosarcoma patients." (PMID 35187070, 2021).